SOX11 (SRY-box transcription factor 11)
Diseases named in the same sentence as SOX11 in open-access papers (continued):
Sharing a sentence is not in itself a finding about the gene and the disease.
neuroblastoma (15 papers, 2010 to 2025). Neuroblastoma (NB) is the most common solid, extracranial childhood tumor. "Here, SOX11 is identified as a potential epigenetic master regulator upstream of the core regulatory circuitry in adrenergic high-risk neuroblastoma." (PMID 36882421, 2023). "Finally, SOX11 is identified as a core transcription factor of the core regulatory circuitry (CRC) in adrenergic high-risk neuroblastoma with a potential role as epigenetic master regulator upstream of the CRC." (PMID 36882421, 2023). "To evaluate the biological role of SOX11 in Neuroblastoma, we further performed SOX11 CUT&RUN under self-renewing and 4 days ATRA-treated KCNR cells." (PMID 38653778, 2024). "However, a recent study has shown that the expression of SWI/SNF is regulated by SOX11 in neuroblastoma, and SOX11 is an ADRN CRC TF serving as a dependency transcription factor in adrenergic neuroblastoma." (PMID 40962798, 2025). "Inversely, SOX11 has been identified as a core transcription factor in adrenergic high-risk neuroblastoma, where SOX11 can regulate the expression of multiple SWI/SNF subunits in adrenergic neuroblastoma cells." (PMID 40832700, 2025). "Given the similarity in stemness between human neuroblastoma cells and NPCs, it is hypothesized that Sox11 plays a similar role in NPC differentiation into neurons." (PMID 40128823, 2025). "In order to illustrate the advantage of HTSplotter on genetic-chemical perturbagen assessed in real-time, we applied our tool to an in-house assessment of exogenous overexpression of the SOX11 gene in the SH-EP neuroblastoma cell line, in combination with the MYB inhibitor celastrol." (PMID 38181013, 2024). "We propose SOX11 as epigenetic master regulator upstream of the core regulatory circuitry involved in co-initiation or establishment and/or maintenance of the adrenergic neuroblastoma core regulatory circuit and cell identity." (PMID 36882421, 2023). "To identify putative functional SOX11 regulated direct targets, we filtered for genes marked by SOX11 promotor binding in combination with significant altered expression levels after SOX11 overexpression in the neuroblastoma cell line SH-EP, both after 9 h (early targets) and 48 h (late targets)." (PMID 36882421, 2023). "To examine whether miR-204 down-regulates Sox11 expression, we utilized mouse neuroblastoma 2a (Neu-2a) cells, which show high expression of Sox11." (PMID 23516376, 2013). "We identified SOX11 as a dependency gene in adrenergic neuroblastoma (NB) which is recurrently affected by large segmental 2 p gains in high-risk NBs as well as recurrent focal gains and amplifications." (PMID 36882421, 2023). "Structural disruption of the BAF complex, achieved by silencing of its essential subunits and direct SOX11 targets ARID1A and ARID1B, exerted an epigenomic reprogramming in neuroblastoma cells, resulting in reduced neuroblastoma invasiveness and metastasis." (PMID 36882421, 2023).
Burkitt lymphoma (14 papers, 2010 to 2024). A rare form of malignant mature B-cell non-Hodgkin lymphoma. "SOX11 is expressed in cyclin D1-negative MCL (classic and blastoid variant) but can be seen in other blastoid neoplasms such as Burkitt lymphoma." (PMID 37530792, 2024). "SOX11 expression has been reported in T-cell and B-cell lymphoblastic lymphoma/leukemia, Burkitt lymphoma, T-cell prolymphocytic leukemia, and rarely in classic Hodgkin lymphoma." (PMID 34888236, 2021). "In agreement with public data, we show that SOX11 is de novo methylated in all Burkitt’s lymphomas, follicular lymphomas and diffuse large B-cell lymphomas." (PMID 25880212, 2015). "Consistent with previous findings, two of four cases of Burkitt’s lymphoma showed moderate nuclear staining of SOX11." (PMID 22738398, 2012). "SOX11 is also expressed in subsets of Burkitt lymphomas, lymphoblastic leukemias and hairy cell leukemias." (PMID 21124928, 2010). "Our recent investigations demonstrated that nuclear staining of SOX11 is also seen in Burkitt Lymphoma (BL) and precursor B and T cell lymphoblastic neoplasia, indicating a more widespread role in lymphoproliferative diseases than initially anticipated as also confirmed by others." (PMID 20624318, 2010). "SOX11 positive cell lines showed strong (Z138, GRANTA-519, SP53, JEKO-1 (all MCL) and KM3 (Acute B lymphoblastic leukemia)), or moderate to weak staining (REC-1 (MCL) and BJAB (Burkitt’s lymphoma)) by SOX11-C1 antibody." (PMID 22738398, 2012). "Apart from MCL, Sox11 is expressed in MCL, lymphoblastic lymphoma, some Burkitt lymphomas, and T-cell prolymphocytic leukemia, but is not known to be expressed in other lymphoid neoplasms." (PMID 27119356, 2016).
Intellectual disability (13 papers, 2016 to 2025). "Mutations in SOX4 and SOX11 cause intellectual disability and other neurodevelopmental alterations, and variants in the TFAP2D locus are associated with bipolar disorder and emotional dysregulation." (PMID 39814878, 2025). "In both cases, the patients exhibited phenotypes that were similar to those of other CSS patients with SOX11 variants, including intellectual disability, dysmorphic facial features, growth delay, and hypoplastic fifth toenails." (PMID 36369738, 2023). "The intellectual disability gene, Sox11, encodes for a critical neurodevelopmental transcription factor with functions in precursor survival, neuronal fate determination, migration and morphogenesis." (PMID 30385877, 2018). "Furthermore, SOX4 and SOX11, members of the SoxC gene group, are both associated with neurodevelopmental delay and intellectual disability." (PMID 39057025, 2024).
prostate carcinoma (13 papers, 2017 to 2025). A carcinoma that arises from epithelial cells of the prostate gland. "In certain human cancers, SOX11 acts as a tumour suppressor, whereas in others, such as prostate cancer, it promotes proliferation, migration and invasion." (PMID 40683913, 2025). "A prognostic model composed of seven protein-coding genes (FOXN4, MGAM, MMP26, ARC, SOX11, PRAME, and VWA5B2) was established, and it was strongly associated with biochemical recurrence following radical prostatectomy in prostate cancer." (PMID 37255653, 2022). "In this respect, a number of novel assay concepts have been reported that detect DNA hypermethylation, a characteristic trait of prostate cancer associated with the epigenetic silencing of key genes such as GST-Pi and SOX11." (PMID 30413115, 2018). "However, SOX11 has been reported to act as a potential tumor suppressor that is down-regulated in prostate cancer and overexpression of SOX11 suppresses migration and invasion in prostate cancer cells in vitro." (PMID 36551589, 2022). "SOX11 has been shown to act as a tumor suppressor in several cancers, including prostate cancer." (PMID 34944472, 2021). "In prostate cancer, elevated SOX11 could suppress the invasive and migrative abilities of prostate cancer cells in vitro, and SOX11 promoter hypermethylation was correlated to adverse clinicopathological properties (Pugongchai, Bychkov, & Sampatanukul, 2017)." (PMID 32043610, 2020). "SOX11, CRISP3, KIF18B, and MELK expression levels have also been found to be positively correlated with poor prostate cancer patient prognostic outcomes, while ZNF556 has been associated with poor colon cancer patient prognosis." (PMID 36245556, 2022). "In contrast, a low expression of SOX11 was frequently observed in other cancers, such as nasopharyngeal carcinoma (NPC), prostate cancer, gastric cancer (GC) and bladder cancer." (PMID 36551589, 2022). "Though up to now SOX11 has not been found to be the downstream of ASCL1 in pulmonary NE cell differentiation, NE differentiation of prostate cancer cells is suggested to be partially mediated by SOX11, and a recent paper shows that SOX11 mRNA is upregulated in pulmonary HG-NECs." (PMID 34996493, 2022).
microcephaly (12 papers, 2016 to 2025). A congenital or acquired developmental disorder in which the circumference of the head is smaller than normal for the person's age and sex. "The role of ZIC2 in neurulation has been well characterized in vivo in mouse 53,54 and genetic variants of SOX11 in humans have been associated with midline defects, microcephaly and ocular malformations 64,65." (PMID 40777478, 2025). "Variants in SOX11 can cause ID, microcephaly, ocular malformation, hypogonadotropic hypogonadism, and dysmorphic features." (PMID 37762546, 2023). "In this study, I will focus on two members of the SOXB1 group (SOX2 and SOX3) and two members of the SOXC group (SOX4 and SOX11) for their associations with microcephaly." (PMID 38094004, 2023). "More recently, a large cohort study revealed that developmental delay (DD) or ID, microcephaly, short stature, and low body weight were common characteristics in patients with SOX11 variants." (PMID 35938035, 2022). "Firstly, SOX11 mutant patients with microcephaly tend to be associated with oculomotor apraxia or abnormal eye morphology, while the ARID1B-related CSS patients usually have a coarse face." (PMID 35938035, 2022). "The precise mechanism by which loss of Sox11 results in microcephaly in Xenopus, however, is still unclear." (PMID 26543203, 2016). "As in other SOX gene-associated brain size defects, the microcephaly phenotype observed in individuals with SOX4 or SOX11 variants has low penetrance, suggesting a complex interplay between SOX genes and other unidentified genes that variably affect the consequences of the SOX gene deficiency." (PMID 38094004, 2023). "Our experiments in Xenopus embryos indicate that loss of Sox11 is associated with microcephaly." (PMID 26543203, 2016). "Knockdown of Sox11 in xenopus laevis was associated with microcephaly in the morphants." (PMID 26543203, 2016). "The fact that both heterozygous deletions and mutations of SOX11 are associated with microcephaly suggests that loss of function and haploinsufficiency may be the underlying mechanism." (PMID 26543203, 2016). "This suggests that SOX11 loss of function can be associated with microcephaly." (PMID 26543203, 2016). "Mice engineered to be conditionally mutant for both Sox4 and Sox11 die at birth with microcephaly and an ear phenotype." (PMID 38094004, 2023). "Moreover, the phenotypic summary of reported patients showed only about one-third of patients had microcephaly, and one-tenth had nail dysplasia, also suggesting differences between SOX11-related phenotypes and classical CSS." (PMID 35938035, 2022). "However, case 5 has borderline microcephaly, while the other individuals in the report of De Rocker et al18 who had similar deletions involving MYT1L but not SOX11 tended to have macrocephaly." (PMID 26543203, 2016).
bladder cancer (10 papers, 2015 to 2025). "A 5-gene panel was identified (NKX6-2, CA10, DBC1, MYO3A, and PENK or SOX11) and the panel had an 85% sensitivity and a 95% specificity for the detection of bladder cancer." (PMID 37627900, 2023). "Eight genes (NKX6-2, A2BP1, CA10, DBC1, MYO3A, NPTX2, PENK, and SOX11) were significantly highly methylated in the urine sediments of bladder cancer patients as compared to that of control subjects." (PMID 37627900, 2023). "RNF144A-AS1 was found to be an oncogene in bladder cancer, which promotes proliferation, migration, and invasion in tumor progression by regulating SOX11 via sponging miR-455-5p." (PMID 34722522, 2021). "In this study, circCEP128 and SOX11 were found highly expression and positively related in bladder cancer tissues." (PMID 30134837, 2018). "In bladder cancer cell lines, SOX11 expressed higher in BIU-87 and TCCSUP compared with RT-112 and 5637." (PMID 30134837, 2018). "We also demonstrate that knockdown of circCEP128 can effectively inhibit cell proliferation and promote cell apoptosis rate of bladder cancer cells through targeting miR-145-5p/SOX11 axis." (PMID 30134837, 2018). "Analysis of clinicopathologic features, circCEP128 and SOX11 showed significant higher expressions in bladder cancer tissues compared with adjacent normal tissue." (PMID 30134837, 2018). "In conclusion, the results of our study demonstrate that circCEP128 is up-regulated in human bladder cancer, and is able to sponge miR-145-5p for promoting SOX11 expression with high efficiency." (PMID 30134837, 2018). "Cell cycle induced bladder cancer cell G1/S arrest in si-cirRNA, miR-145-5p mimics and si-SOX11 group (P < 0.01)." (PMID 30134837, 2018). "In present study, circCEP128 and SOX11 were observed significantly up-regulated in bladder cancer tissues, while the expression of miR-145-5p was decreased in cancer samples compared to normal samples." (PMID 30134837, 2018). "SOX11 methylation was also used in a five-gene biomarker panel to detect bladder cancer at an early stage." (PMID 25880212, 2015). "As previous studies have reported, miR-145-5p could repress the progression of bladder cancer by regulating SOX11; further, miR-145-5p could suppress the progression of laryngeal squamous cell carcinoma via FSCN1." (PMID 32706759, 2020). "Furthermore, CEP128 acts as a ceRNA to regulate SOX11 by sponging miR-145-5p, thereby reducing the inhibitory effect of miR-145-5p on SOX11 in bladder cancer." (PMID 31213578, 2019). "Therefore, it was verified that circCEP128 acted as a ceRNA for miR-145-5p to regulate SOX11, which further promoted cell proliferation and suppressed cell apoptosis of bladder cancer." (PMID 30134837, 2018). "The down-regulation of miR-145-5p was speculated as a competitive target of circCEP128 and SOX11 in bladder cancer." (PMID 30134837, 2018). "We hypothesized that circCEP128 might function as a competing endogenous RNA (ceRNA) for miR-145-5p in regulating SOX11, which might further inhibit cell proliferation and promote cell apoptosis of bladder cancer." (PMID 30134837, 2018). "In this study, SOX11 was a contributor to bladder cancer in terms of proliferation and apoptosis." (PMID 30134837, 2018). "CircCEP128 functions as a ceRNA for miR-145-5p, which could up regulates SOX11 and further promotes cell proliferation and inhibits cell apoptosis of bladder cancer." (PMID 30134837, 2018). "Furthermore, GRASLND promotes bladder cancer progression through the miR-455-5p/SOX11 axis." (PMID 39060946, 2024). "Therefore, we hypothesized that SOX11 might be regulated by miR-145-5p in human bladder cancer." (PMID 30134837, 2018).
gastric cancer (9 papers, 2014 to 2025). A primary or metastatic malignant neoplasm involving the stomach. "Our data suggested an association between SOX11 expression and improved overall survival in gastric cancer patients." (PMID 24604109, 2014). "Previously, elevated SOX11 expression was observed in various cancer types, including brain, breast, head and neck, and gastric cancers." (PMID 34442467, 2021). "Of the gastric cancer tissues 51.7% (78 of 151) showed positive SOX11 staining (IHC score: 4–12), and 48.3% (73 of 151) of the samples showed negative staining (IHC score: 0–3)." (PMID 24604109, 2014). "To investigate the role of SOX11 in the growth of gastric cancer cells, we first examined the cell proliferation in monolayer culture." (PMID 24604109, 2014). "As peritoneal spreading and metastasis are common in gastric cancer and are pivotal factors for its poor prognosis, we used a nude mouse model to investigate the influence of SOX11 levels on peritoneal metastasis." (PMID 24604109, 2014). "SOX11 was a potential tumor-suppressor and an independent positive prognostic factor in gastric cancer patients with less advanced clinicopathological features." (PMID 24604109, 2014). "In order to examine the effects of SOX11 on the in vivo growth of gastric cancer cells, we employed two experimental models." (PMID 24604109, 2014). "SOX11 overexpression suppressed migration and invasion ability of gastric cancer cells in vitro and in vivo." (PMID 24604109, 2014). "SOX11-overexpressing gastric cancer cells showed suppressed migration and invasion malignant behavior." (PMID 24604109, 2014). "From the Oncomine database, we found that SOX11 was overexpressed in intestinal-type gastric cancer." (PMID 24604109, 2014). "We performed qRT-PCR and immunoblotting to analyze the SOX11 mRNA and protein levels in gastric cancer cell lines and GES-1." (PMID 24604109, 2014). "The aim of this study was to investigate the role of SOX11 in gastric cancer and its expression pattern and clinical significance." (PMID 24604109, 2014). "We then analyzed the SOX11 expression in human gastric cancer cell lines and the immortalized normal gastric epithelial cell line GES-1." (PMID 24604109, 2014). "In concusion, our findings demonstrate that SOX11 suppresses gastric cancer migration and invasion in vitro and in vivo." (PMID 24604109, 2014). "We performed immunohistochemistry staining to examine the SOX11 protein expression in gastric cancer tissues." (PMID 24604109, 2014). "To investigate the prognostic significance of SOX11 in gastric cancer, we analyzed the correlation of SOX11 with survival of patients using Kaplan-Meier analysis." (PMID 24604109, 2014). "Consistent with database analysis, we showed that SOX11 mRNA and protein levels were highly expressed in all gastric cancer cell lines compared to GES-1." (PMID 24604109, 2014). "Additionally, SOX11 was found to be an independent prognostic factor for improving survival in gastric cancer." (PMID 36551589, 2022). "SOX11 may serve as a marker for a subgroup of gastric cancer which shows less aggressive features and better prognosis." (PMID 24604109, 2014). "We uncovered SOX11 as a prognostic factor for improved survival in gastric cancer patients." (PMID 24604109, 2014). "SOX11 is an independent prognostic factor for improved survival in gastric cancer patients." (PMID 24604109, 2014). "As gastric cancer patients are often diagnosed at advanced stage, the prognostic value of SOX11 in advanced stage patients could be of great importance in predicting patient survival." (PMID 24604109, 2014). "We further examined the expression and clinical significance of SOX11 in gastric cancer." (PMID 24604109, 2014). "Specifically, SOX11 is expressed in early stage, differentiated and intestinal-type gastric cancer." (PMID 24604109, 2014).